HSP90AB6P (heat shock protein 90 alpha family class B member 6, pseudogene)
Gene: Processed pseudogene on chromosome 13 (96,883,842 to 96,885,821, reverse strand). Ensembl gene ENSG00000235137.
Diseases named in the same sentence as HSP90AB6P in open-access papers:
HSP90AB6P is named in the same sentence as 2 diseases in open-access papers, as found by Europe PMC text mining. Sharing a sentence is not in itself a finding about the gene and the disease.
HSP90AB6P shares sentences with these, for which no sentence is quoted: lung carcinoma (1 paper); tumour (1).